NOX4 (NADPH oxidase 4)
Diseases named in the same sentence as NOX4 in open-access papers (continued):
Sharing a sentence is not in itself a finding about the gene and the disease.
tumor (continued). "By analyzing TCGA data, the expression of NOX4 was significantly correlated with tumor stage and grade." (PMID 33499904, 2021). "NOX4 has previously been suggested to function as a mitochondrial energy sensor and glycolytic regulator in tumor cells." (PMID 34944680, 2021). "The role of TGF-β in tumorigenesis is controversial, since it induces both NOX1 and NOX4 expression in hepatocytes, acting as a tumor suppressor in the early phases of tumor development but also promoting invasiveness and metastasis in advanced cancer." (PMID 34204571, 2021). "The high expression of NOX4 in GBC tumor/stroma is closely related to VM formation, and indicates poor prognosis." (PMID 33153467, 2020). "mTOR is primarily involved in regulating the NOX4, which are involved in cancer-related signaling and are closely related to the occurrence and development of tumours." (PMID 33335853, 2020). "All together, these results confirmed that the expression of NOX4, especially in the tumor stroma, is an independent prognostic factor of GBC." (PMID 33153467, 2020). "All together, these results suggested that GCAFs promote VM formation and tumor growth in GBC via upregulating NOX4 expression through paracrine IL-6 mediating IL-6/JAK/STAT3 signaling pathway." (PMID 33153467, 2020). "The mean, median and a 5-year survival rate for survival time of the high NOX4 expression in tumor cells (50/85, 58.8%) were 15.6 months 5.8 months and 10.5%, compared with 30.5 months 25.0 months and 22.2% for the low NOX4 expression (35/85, 41.2%)." (PMID 33153467, 2020). "All together, these results firstly suggested that GCAFs promote VM formation and tumor growth in GBC via upregulating NOX4 expression through paracrine IL-6 mediating IL-6/JAK/STAT3 signaling pathway." (PMID 33153467, 2020). "It was reported that the activation of STAT5 acts as a tumor suppressor via controlling the expression of ROS-induced NOX4 and two proapoptotic proteins, PUMA and BIM, in the liver tissue." (PMID 31511651, 2020). "IHC was used to validate the abundance of IFI6, ATF3 and NOX4 in tumor tissues derived from xenograft model." (PMID 32727517, 2020). "NOX4-mediated cancer metastasis was further confirmed in our studies by the depletion of NOX4, which significantly inhibited OA-induced extravasation and tumor nodule formation in the lungs of mice." (PMID 32641980, 2020). "GCAFs promote VM formation and tumor growth in GBC via upregulating NOX4 expression through the activation of IL-6-JAK-STAT3 signal pathway." (PMID 33153467, 2020). "NOX4, which has a prominent role in cancer and tumor stroma progression, shows an increased average Log2 median-centered intensity in thyroid tumorigenesis." (PMID 29478325, 2019). "Treatment with the previously available NOX1/NOX4 inhibitor GKT831 also suppressed B16-F10 tumor growth, whereas it had only a weak effect on MC38 tumors." (PMID 31249132, 2019). "Mechanistically, TGFβ secreted into the tumor environment causes phosphorylation of the SMAD2/3, SMAD complex and JNK activation, which in turn increases NADPH oxidase NOX4 synthesis." (PMID 29478325, 2019). "NOX1, NOX2, and NOX4 expression in cancer cells promotes tumor growth and metastasis in several cancers, including melanoma, gastric, pancreatic, and colon tumors." (PMID 31249132, 2019). "Treatment of mice with anti-sense Nox4 showed a significant reduction in tumor size as compared to sense-Nox4- or PBS-treated groups." (PMID 29491408, 2018). "Growing evidence confirms that there is a close correlation of Nox4 with cancer development and progression and the inhibition of Nox4 suppresses tumor growth and leads to cancer cell death." (PMID 30513726, 2018). "Consistent with this, NOX4 inhibition also abrogated CAF-dependent tumor cell migration/invasion in Transwell and organotypic culture assays." (PMID 28922779, 2018).
tumor (continued). "We postulate that Nox4 overexpression accounts for a novel mechanism that contributes to tumor progression and poor clinical outcome in patients with OTSCC." (PMID 30513726, 2018). "Findings identify stromal Nox4 as a central mediator of reciprocal epithelial‐stromal cell crosstalk, fibroblast activation and stromal‐driven tumor (cell)‐promoting hallmarks." (PMID 29441570, 2018). "Consistent with the in vitro studies, NOX1 and NOX4 were greatly upregulated in tumor xenografts treated with PJ-34." (PMID 29684820, 2018). "Not surprisingly, silencing of NOX4 efficaciously blocked the distant metastasis of GC and therapy using plumbagin, a specific inhibitor of NOX4, inhibited the progression of GC in tumor-bearing mice, which was in accordance with the in vitro findings." (PMID 30237423, 2018). "NOX4’s role in CAF-mediated tumor progression was assessed in vitro, using CAFs from multiple tissues in Transwell and organotypic culture assays, and in vivo, using xenograft (n = 9–15 per group) and isograft (n = 6 per group) tumor models." (PMID 28922779, 2018). "RNA in situ hybridization revealed significantly elevated Nox4 mRNA levels predominantly in the peri‐tumoral stroma of clinical PCa with intense stromal Nox4 staining adjacent to tumor foci expressing abundant TGFβ protein levels." (PMID 29441570, 2018). "Similar results were observed on the PCa TMA with Nox4 mRNA levels significantly elevated in both tumor epithelial and peritumoral stromal cells in PCa compared to patient‐matched benign regions." (PMID 29441570, 2018). "Paradoxically, Nox4 expression is not only needed for proliferation but also for apoptosis of tumor cells." (PMID 28620580, 2017). "We also found higher relative mRNA expression of Nox4 and higher levels of direct Nox4-RyR1 binding compared to non-tumor control mice." (PMID 29312148, 2017). "As molecules like NOX4 and ROS themselves have critical functions in neoplasia, the ramifications of juxtaposing these pro-tumor factors will have great impact in better understanding how cancer evades current therapeutic regimens." (PMID 28423654, 2017). "The TGFβ signal mediator SMAD3 is phosphorylated in mice with 4T1 OCIB and that the relative expression of Nox4 mRNA and Nox4-RyR1 binding is higher than in non-tumor control mice." (PMID 29312148, 2017). "Accumulating evidence has revealed that NOX4 plays an important role in several types of tumor cells, leading to different outcomes." (PMID 28422720, 2017). "In vivo, inhibition of NOX4 expression by siRNA, abrogated tumorigenesis, cell invasion, and tumor growth in a murine xenograft model of RCC." (PMID 29065504, 2017). "At 12 months, the non-tumor (NT) areas also showed differential expression of Nox4 compared with that in the corresponding tumor samples (30% and 5.8%, respectively) (12M NT vs 12M T) (***P≤0.0001)." (PMID 27895046, 2017). "We also established the inducible NOX4-konckdown cell line (AsPc-1/i-shNOX4), and revealed that ‘Dox/on' group mice showed a significant reduction in tumour burden compared with the control group after 4 weeks of dox treatment." (PMID 28232723, 2017). "Meanwhile, multivariate analysis identified that NOX4 expression, tumor size and distant metastasis were independent prognostic factors in patients with CRC." (PMID 28422720, 2017).
tumor (continued). "Here, we present comprehensive characterization of a novel NOX4 monoclonal antibody raised to an extracellular domain, and demonstrate its utility for investigating the role of NOX4 in tumor biology." (PMID 28578276, 2017). "Compelling evidence demonstrates that NOX4 and its generated ROS have a close relation to tumor angiogenesis in different cancers." (PMID 28594389, 2017). "The experimental results presented and discussed herein lead to a still hypothetical but consistent picture of the role of the NADPH oxidase, Nox4, in cellular growth in normal and tumor cells." (PMID 28620580, 2017). "Insights into the role of NOX4 in tumor biology, provided by IHC, demonstrate marked overexpression of NOX4 in several malignancies, several for the first time." (PMID 28578276, 2017). "We discovered NOX4 overexpression was significantly associated with CRC metastasis depending on clinicopathological data and GSEA analysis, thus the role of NOX4 in tumor cell migration and invasion was investigated." (PMID 28422720, 2017). "Nox4 which in the two tumor cell lines studied here is a NADPH oxidase of the ER, directly (without the help of superoxide dismutase) produces H2O2 as a growth-related signaling substance." (PMID 28620580, 2017). "Next, we investigated the effect of NOX4 on the kinetics of PDAC tumour progression by subcutaneous injection." (PMID 28232723, 2017). "Univariate analysis showed that NOX4 expression, tumor size, T classification and distant metastasis were significantly associated with a poorer clinical outcome in CRC cases." (PMID 28422720, 2017). "According to the proliferation and apoptosis pathways in GSEA, we found GLI1, a well-known transcription factor involved in the growth of many human tumours, was active in patients with higher NOX4 expression." (PMID 28422720, 2017). "In this report, we used HeLa cells to examine the role of NOX4 in the proliferation and invasion of tumor cells and previous studies showed the antioxidant treatment in HeLa cells inhibits the cell proliferation and invasion." (PMID 28099519, 2017). "Application of our antibody to a human tumor tissue microarrays has provided novel insights into the expression of NOX4 in human tumors." (PMID 28578276, 2017). "NOX4 levels were substantially higher in these tumours than in histologically normal pancreata from control mice." (PMID 28232723, 2017). "Global genetic ablation of Nox1 was shown to impair tumour angiogenesis in mice, while (again global) genetic deletion of Nox2 or Nox4 was reported to reduce blood flow recovery in ischemic mouse hindlimb models." (PMID 28433660, 2017). "In the present article, we present evidence that Nox4, similar to its yeast homolog, creates a ROS signal leading to re-structuring of the actin cytoskeleton in two human tumor cell lines." (PMID 28620580, 2017). "As IL-6/STAT3 signaling can promote proliferation and survival of NSCLC cells, these data suggest that NOX4-induced IL-6 expression, at least partly, accounts for its tumor-promoting effect." (PMID 25504436, 2015). "Here we investigated the effects of Nox4 on GBM tumor cell invasion, angiogenesis, and radiosensitivity." (PMID 24868315, 2014). "p.)reduced the tumor volume of NOX4-transduced tumor-harbored mice to the level comparable to that of vector-control group." (PMID 24946933, 2014). "Overall, these results point to NOX4 as an important mediator of oncogenic functions, specific for the neoplastic condition and common among several tumor types." (PMID 24583638, 2014). "The capability of NOX4 overexpression to promote NSCLC aggressiveness was also examined using an in vivo tumor model." (PMID 24946933, 2014).
tumor (continued). "We conclude that Nox4 is a critical mediator of the tumor microenvironment under cycling hypoxia, and mediates ROS production in GBM." (PMID 21935366, 2011). "NADPH oxidase subunit 4 (Nox4) RNAi-knockdown technology was utilized to study the role of Nox4 in cycling hypoxia-mediated ROS production and tumor progression." (PMID 21935366, 2011). "Nox4 knockdown or Tempol treatment suppressed tumor ROS and tumor growth in cycling hypoxia-treated mice and control mice." (PMID 21935366, 2011). "Flow cytometric analysis indicated that CM-DCFDA and DHE double-positive populations in implanted tumor cells were strongly reduced by NOX4 gene silencing, which was consistent with in vitro experimental data." (PMID 22032647, 2011). "We utilized BLI for assessing intracranial tumor response to cycling hypoxia, Nox4 knockdown, and Tempol treatment in the orthotopic GBM8401-Luc xenograft model." (PMID 21935366, 2011). "Here, we highlighted how the tumor microenvironment, cycling hypoxia, increased tumor cell ROS via Nox4 and further promoted tumor growth in GBM." (PMID 21935366, 2011). "In cancer biology, NOX4 plays a dual role: while physiological ROS signaling supports normal cellular processes, pathological NOX4-driven ROS production contributes to genomic instability, tumor progression, and resistance to targeted therapies." (PMID 41562694, 2026). "The network further illustrated that NOX4 influences the expression of key immunomodulatory cytokines and immune checkpoint proteins, including IL-8 and PD-L1, which are critical mediators of tumor immune evasion and therapeutic resistance." (PMID 41562694, 2026). "These NK cells exert a considerable influence on tumor defense, so it may be implied that high NOX4 expression may reflect stronger immune surveillance." (PMID 40061897, 2025). "In contrast, expressions of TIMP1 and NOX4 exhibited significant positive correlations with immune infiltration, implying that these genes could be enhancing immune cell presence in the tumor microenvironment." (PMID 40290432, 2025). "Indeed, we described here how setanaxib was able to reduce iCCA tumour growth as well as intratumoural fibrosis, correlating with the fact that NOX4 is mainly concentrated in myCAF, which produce ECM." (PMID 40820091, 2025). "The current study utilized NOX4 inhibitors to lower ROS levels, which may help slow down tumor progression." (PMID 40061897, 2025). "Additionally, inositol 1,3,4,5-tetrakisphosphate (IP4), generated by ITPKB, mitigates cisplatin-induced oxidative stress by suppressing NADPH oxidase 4 (NOX4), thereby supporting tumor survival." (PMID 41462961, 2025). "Additionally, NOX4 expression increased with higher tumor stages in BLCA, SKCM, ESCA, COAD, STAD, THCA, and TGCT." (PMID 38663913, 2024). "Additionally, its correlation with advanced tumor stages across various cancers suggests a role for NOX4 in driving tumor progression." (PMID 38663913, 2024). "Additionally, the increase of iron-activated Nox4 leds to excessive production of hydrogen peroxide and lipid peroxides, inducing ferroptosis in tumor cells." (PMID 38388534, 2024). "Additionally, another group has suggested NOX4 as a key player in TGFβ-induced epithelial-to-mesenchymal transition and migration of non-tumor and metastatic human breast cells." (PMID 38542437, 2024). "Furthermore, the study demonstrated a robust correlation between NOX4 expression and immune cell infiltration, signifying its involvement in the modulation of the tumor microenvironment." (PMID 38663913, 2024). "Similarly, Qiao and colleagues investigated the role of NOX4 in GC by observing its upregulation in the tumor mass compared with adjacent non-tumor tissues, which was correlated with higher invasive capability and a worse TNM stage." (PMID 37371466, 2023).
tumor (continued). "Furthermore, inhibition of ERK using U0126 partially blocked OA-induced ANGPTL4 expression but dramatically inhibited IL-8 and NOX4 expression, followed by the inhibition of tumor cell invasion." (PMID 37649607, 2023). "In most tumor types, NOX4 significantly promotes tumor development." (PMID 36874093, 2023). "Additionally, we evaluated NOX4 protein expression in infiltrating PTC tumors, characterized by the infiltration of tumor borders and consequently presenting a risk of metastasis initiation." (PMID 37504283, 2023). "MicroPET imaging was used to further verify the effects of NOX4 on tumor glucose uptake." (PMID 37670970, 2023). "MicroPET imaging was used to detect the effects of NOX4 on tumor metabolism." (PMID 37670970, 2023). "Similarly, inhibition of NOX4 acts synergistically with HER3 inhibition to decrease tumor growth in OC." (PMID 35743145, 2022). "From a clinical standpoint, a recent study provided encouraging data demonstrating that the NOX4 inhibitor GKT137831 (Setanaxib) was capable of overcoming immunotherapy resistant tumor growth by suppressing the exclusion of CD8+ T-cells from the tumor cells’ environment in in vivo rodent models." (PMID 35269843, 2022). "However, because TGF-β is important for tissue homeostasis, targeting its downstream targets such as NADPH oxidase 4 (NOX4) can be a safer approach to restoring T cell anti-tumor activity restricted by TGF-β." (PMID 35345849, 2022). "The up-regulation of NOX4 promotes tumor angiogenesis by stabilizing HIF-1α in mice." (PMID 36297636, 2022). "Nox4 is a critical mediator of ROS production and tumor progression." (PMID 36278207, 2022). "Moreover, MI inhibited xenograft tumor growth in vivo and decreased the expression of Nox4, NF-κB, and HIF-1α." (PMID 35293283, 2022). "NOX4 acts as an oxygen sensor for catalysis of molecular oxygen in various reactive oxygen species (ROS), and the resulting ROS undergo many biological reactions, including those involved in signal transduction, cell differentiation, and tumor cell growth." (PMID 35346198, 2022). "Moreover, the increased levels of ROS result from the upregulation of the NADPH oxidase subunit NOX4, which serves as the main contributor to ROS production in OC cells to promote tumor growth and angiogenesis." (PMID 35743145, 2022). "Finally, GLX351322, an inhibitor targeting NOX4, was used to inhibit NOX4-derived ROS in vitro and detect its effect on drug resistance of tumor cells in vivo." (PMID 35396551, 2022). "For instance, NOX4 inhibitor could restrain fibroblast activation resulting from stimulation of surrounding tumor cells, indicating the value of NOX4 blockade as a stromal-targeted strategies." (PMID 35646942, 2022). "The NOX4-driven system of endogenous ROS production demonstrates a new mechanism in OC cells to promote tumor development, angiogenesis, and an increase in therapeutic resistance through the upregulation of HER3, reflecting a candidate for targeted therapy of treatment-resistant OC." (PMID 35743145, 2022). "NOX4 exhibits upregulated expression in GC tumor tissue compared with adjacent normal tissues." (PMID 35646942, 2022). "Important findings of our work described here are that NCX4040 induces a significant amount of ROS/RNS generation by inducing NOX4 enzymes which are responsible for the generation of O2•− in tumor cells, and induction of CHAC1 which leads to depletion of cellular GSH and oxidative stress." (PMID 36612280, 2022). "The role of NOX4 has been previously studied in the TGFβ signalling pathways in different tumours, but its role downstream of TGFβ in GBM, and specifically in GSCs, is still unknown." (PMID 35203105, 2022). "NOX4-induced ROS production could activate various oncogenic signaling pathway, rewire metabolic phenotype of tumors and reprogram the tumor stroma." (PMID 35646942, 2022). "Besides, it is necessary to exploit potential biomarkers that sensitize tumor cells for NOX4 blockade." (PMID 35646942, 2022).